KRAS (KRas proto-oncogene, GTPase)
Diseases named in the same sentence as KRAS in open-access papers (continued):
Sharing a sentence is not in itself a finding about the gene and the disease.
pancreatic cancer (continued). "In pancreatic cancer, activating mutations lock KRAS in its active state, leading to uncontrolled cell proliferation, survival, and tumor progression." (PMID 40806294, 2025). "For example, in pancreatic cancer patients, mutations in KRAS in ctDNA have been found to correlate with prognosis." (PMID 40433362, 2025). "In particular, adoptive cell therapy (ACT) targeting KRAS mutations represents another key research area in the pursuit of personalized treatment for pancreatic cancer and holds great potential for future applications." (PMID 40149381, 2025). "For instance, the majority of pancreatic cancers bear mutation in KRAS protein that can give rise to a predictable neoantigen." (PMID 40437549, 2025). "While KRAS G12C-mutant pancreatic cancer has been treated with Sotorasib, this mutation is relatively rare, occurring in only 2–3% of PDAC cases." (PMID 40305202, 2025). "Whereas the role of oncogenic KRAS mutations is well characterized, the relevance of the partnering wild-type (WT) KRAS allele in pancreatic cancer is less well understood and controversial." (PMID 39412982, 2025). "Since it was first reported in 1994 that KRAS mutations identical to those in tumor tissues were detectable in the plasma cfDNA of a patient with pancreatic cancer, research on ctDNA has advanced rapidly." (PMID 39920551, 2025). "For example, sotorasib and adagrasib are selective, small molecule inhibitors of KRAS-G12C that are approved for non-small cell lung cancer and pancreatic cancer, which have the KRAS-G12C mutation." (PMID 40076613, 2025). "Given that KRAS mutations are detected in approximately 95% of pancreatic cancers, we believe the organoid establishment process utilized in our study would be broadly applicable to the majority of pancreatic cancer cases." (PMID 40462147, 2025). "The KRAS proto-oncogene is mutated in pancreatic cancer, leading to rapid proliferation of tumor cells and the onset of oncogenesis." (PMID 39810420, 2025). "Beyond its well-established oncogenic functions, emerging evidence suggests that pathogenic KRAS variants also contribute to shaping the immunosuppressive phenotype of the tumor microenvironment including lung and pancreatic cancers." (PMID 40981070, 2025). "Flow cytometry showed that the protein binds specifically to pancreatic cancer cells with KRAS G12V mutation in Capan-1 and CFPAC-1 as well as to human T cells." (PMID 41472736, 2025). "In PDAC, Gal-3 directly binds and stabilizes active GTP-bound Ras proteins, sustaining downstream MAPK/ERK and PI3K/AKT signaling, which is particularly relevant given the high prevalence of KRAS mutations in pancreatic cancer." (PMID 41153387, 2025). "Both have a mutation for the proto-oncogene KRAS, which is the most common event in pancreatic cancer initiation and progression (~ 90%) of PDACs and can reflect human disease progression." (PMID 41145806, 2025). "Most pancreatic cancers, approximately 90%, feature activating mutations in the KRAS oncogene, with specific mutations, such as G12D, G12V, and G12C, being the most prevalent." (PMID 40895848, 2025). "In KRAS-driven pancreatic cancer, loss of either Parkin or PINK1 increases tumor burden and metastasis, suggesting that these proteins play an early tumor-suppressive role through mitochondrial maintenance." (PMID 41138746, 2025). "Gain-of-function variants of KRAS occur in the early stages of pancreatic cancer, before its progression to invasive carcinoma." (PMID 40981070, 2025).
pancreatic cancer (continued). "Approximately 90% of pancreatic cancers exhibit KRAS mutations, and approximately 40% of these cases harbor the KRASG12D mutation." (PMID 39400496, 2025). "For example, in pancreatic cancer cells with KRAS G12D mutations, the activity of the axis up-regulates ubiquitin-conjugating enzyme UBE2T and modulates the pentose phosphate pathway, which is important for the carbon metabolism of cancer cells." (PMID 40699853, 2025). "Many studies have shown that KRAS mutation in pancreatic cancer is significantly correlated with shorter overall survival, whereas only a few studies have shown an absence of a correlation." (PMID 40002297, 2025). "GSTP is notably overexpressed in various cancers, particularly those with KRAS mutations, such as lung, colorectal, and pancreatic cancers." (PMID 40390497, 2025). "We first compared the uptake of these statin-dye conjugates in two distinct pancreatic cancer cell types: Panc1, featuring a KRAS G12D mutation (KRASG12D), and BxPC3 with KRASWT using confocal microscopy." (PMID 40501736, 2025). "Although KRAS mutations have been associated with several cancer types, 190/215 (88%) of these mutations were found in pancreatic cancers." (PMID 40841759, 2025). "Subgroups with KRAS-mutated cell lines exhibited diverse inter-tumor heterogeneities, representing the complexity of pancreatic cancer." (PMID 39972450, 2025). "Oncogenic point mutations of the KRAS gene can be detected in > 90% of pancreatic carcinomas and, along with the alterations for CDKN2A, are among the early events in carcinoma development." (PMID 39807486, 2025). "The aim of this study was to evaluate the performance of KRAS-mutated cftDNA detection-based liquid biopsy of plasma and bile in patients with pancreatic neoplasms using digital droplet PCR." (PMID 38255325, 2024). "Reports focusing on glycan conformational changes associated with KRAS mutations are scarce in pancreatic cancer, and this is the first report using organoids to analyze glycan changes associated with KRAS mutations." (PMID 38528852, 2024). "The greatest predictors for pancreatic cancer included KRAS gene mutation, age, alcohol consumption status, pancreatitis, and hyperlipidemia." (PMID 39640479, 2024). "KRAS gene mutations arise early in the development of pancreatic cancer, occurring in at least 80% of PDAC cases." (PMID 39456638, 2024). "In conclusion, ZDHHC20, upregulated by KRAS, is abnormally overexpressed and associated with poor prognosis in patients with pancreatic cancer." (PMID 38821916, 2024). "This group also reported that dMMR tumors were less likely to have mutations in traditional pancreatic cancer markers such as KRAS and SMAD4, but rather showed mutations in JAK1 and ACV2RA which correspond with microsatellite instability." (PMID 39458133, 2024). "KRAS-dependent gene signatures have been reported to be associated with sensitivity to decitabine in selected patients with KRAS-mutated pancreatic cancer." (PMID 38829622, 2024). "KRAS mutations, occurring early in pancreatic cancer progression, activate multiple signaling pathways, including Raf/mitogen-activated protein kinase and Akt/protein kinase B, influencing COX-2 transcription." (PMID 38666907, 2024). "They vaccinated 24 patients who had their pancreatic cancer removed and showed KRAS mutations with a 21-mer peptide vaccine containing their tumor’s KRAS mutation." (PMID 38732150, 2024). "Another phase I trial is currently investigating the use of the MEK inhibitor binimetinib in combination with HCQ in KRAS-mutated pancreatic cancer patients with at least one prior treatment line for metastatic disease (NCT04132505)." (PMID 39352477, 2024). "KRAS mutations are found in 32% of lung cancer, 40% of colorectal cancer, and 85% to 90% of pancreatic cancer cases." (PMID 38607003, 2024).
pancreatic cancer (continued). "Specifically in pancreatic cancer, G12D (33–52%), G12V (23–36%) and G12R (11–20%) are among the most common KRAS mutations." (PMID 39329989, 2024). "KRAS gene mutation, age, alcohol consumption status, pancreatitis status, and hyperlipidaemia status are the strongest predictors of pancreatic cancer." (PMID 39640479, 2024). "Given that the pancreatic cancer cell lines applied in the current study both harboured KRAS mutation, the most frequent genetic mutation observed in pancreatic cancer, we were interested in investigating if EPLIN is involved in the KRAS networks." (PMID 39730634, 2024). "Pancreatic cancer is characterized by the accumulation of numerous genetic alterations, with early occurrences of KRAS mutations and EGFR gene amplification occurring during disease progression." (PMID 39087024, 2024). "Over 90 percent of PDAC harbor somatic mutations in the KRAS gene, making it a central focus in pancreatic cancer research and treatment strategies." (PMID 39457488, 2024). "This review will discuss the clinical impact of KRAS mutation status and the outlook of using KRAS mutation information to detect and treat pancreatic cancers." (PMID 38610868, 2024). "Oncogenic KRAS mutations are observed in approximately 90% of pancreatic cancers and less frequently in other cancer types." (PMID 38573819, 2024). "Mutations in the KRAS oncogene are a significant driver of pancreatic cancers, as it is associated with 85–90% of pancreatic tumors (of which approximately 85% of all pancreatic cancers are PDACs)." (PMID 38893220, 2024). "Among HRAS, NRAS, and KRAS, KRAS is involved in the most frequently mutated oncogene in human cancers, accounting for approximately 25% of lung, 40% of colorectal, and 95% of pancreatic cancers." (PMID 38792177, 2024). "To check the mutational status of the epithelial subclusters, we evaluated the sequences of the G12 site of KRAS gene, which is the most common driver mutation site for pancreatic cancer." (PMID 38297291, 2024). "KRAS mutations play a critical role in the development and progression of several cancers, including non-small cell lung cancer and pancreatic cancer." (PMID 39252322, 2024). "Mutations in KRAS are an early oncogenic event in pancreatic cancer and are thought to be an initiating event." (PMID 38730578, 2024). "The increased SAM content and DNA methylation with upregulated DNA methyltransferases suggest metabolic reprogramming coupled with epigenetic alterations contribute to oncogenic effects of LKB1 deficiency in KRAS mutant pancreatic cancer cells." (PMID 39544365, 2024). "Despite the high prevalence of KRAS mutations in pancreatic cancers, only a limited number of cases harbor an actionable point mutation, which poses a challenge for targeted therapies." (PMID 38666907, 2024). "Pancreatic cancer, a malady notorious for its resistance to treatment, harbors a high prevalence of KRAS mutations and thus calls for the development of RAS/MAPK pathway inhibitors." (PMID 38842946, 2024). "Another notable example is the KRAS mutation, one of the most frequently mutated genes in 30% of lung, 50% of colon, and 90% of pancreatic cancers." (PMID 39329989, 2024). "The plethora of new agents under investigation has the potential to revolutionize the treatment paradigm for patients with KRAS-mutated pancreatic cancer." (PMID 38576709, 2024). "One of the predominant mutant KRAS G12D variants is responsible for pancreatic cancer and is an attractive drug target." (PMID 38794122, 2024).
pancreatic cancer (continued). "In this study, we illustrate the co-mutation landscape of KRAS mutations and the allele-specific associations of KRAS-mutated pancreatic cancer with clinical outcome in our institution." (PMID 38310130, 2024). "KRAS, a pivotal oncogene in pancreatic cancer, is frequently mutated, particularly at the G12D residue, driving the pathogenesis of PDAC in roughly 90% of cases." (PMID 39682281, 2024). "KRAS mutations (eg, G12C, G12D, G12V, G13D, inter al.)are drivers of numerous cancer types, including non-small cell lung, colorectal, and pancreatic cancers." (PMID 42064400, 2024). "The primary cause of human pancreatic cancer is typically a single missense mutation in the KRAS gene, specifically affecting the 12th codon and resulting in a substitution of valine or aspartate for glycine, ultimately leading to protein activation." (PMID 38827026, 2024). "The stepwise progression from intraepithelial neoplastic lesions to adenocarcinoma in pancreatic cancer involves early events of oncogenic KRAS mutations." (PMID 38666907, 2024). "Engineered exosomes as carriers for chemotherapeutic drugs and targeted RNA demonstrate potential for treating pancreatic cancer and its metastasis, including strategies targeting KRAS gene mutations, offering new directions for therapy." (PMID 38954230, 2024). "Recent research efforts have been directed toward targeting KRAS, which is the predominant somatic mutation and a key oncogenic driver in pancreatic cancer." (PMID 38732320, 2024). "KRAS is a frequently mutated gene in various cancers, including pancreatic cancer, colorectal cancer, and lung adenocarcinoma." (PMID 38732150, 2024). "We also identified the synergistic effects between KRAS mutation and other risk factors, offering new insights into the genetic and biological mechanisms of pancreatic cancer development." (PMID 39640479, 2024). "The dysregulation of KRAS function due to mutation underscores its pivotal role in driving aberrant cellular activities associated with pancreatic cancer." (PMID 39087024, 2024). "Very recently, the involvement of TMEJ has been implicated in the development and metastasis of KRAS mutated pancreatic cancer and its expression has been associated with a better response to immunotherapy in a subset of bladder cancer patients." (PMID 39435280, 2024). "Both logistic regression and machine learning algorithms confirmed that KRAS gene mutation, hyperlipidaemia and pancreatitis are potential risk factors for pancreatic cancer." (PMID 39640479, 2024). "In contrast, KRAS G12C mutations are less common, manifesting in only 1% to 2% of pancreatic cancer cases." (PMID 38250721, 2024). "Frequent occurrences of KRAS mutations characterize the pancreatic cancer, with G12V and G12D mutations being the most prevalent, collectively representing approximately 90% of cases." (PMID 38250721, 2024). "The present study was designed to explore the expression of ferritin subunits and KRAS mutation status in pancreatic cancer." (PMID 39294443, 2024). "In pancreatic cancer (PC), activating mutations in KRAS are detected in up to 90% of cases, which makes it the prototypical Ras-driven cancer." (PMID 39518045, 2024). "Roughly one of three lung cancers, one of two colon cancers, and nine of ten pancreatic cancers have KRAS mutations." (PMID 38800401, 2024). "They examined the expression of different ferritin components and their link with the KRAS mutation, a common characteristic in pancreatic cancer that promotes tumor growth." (PMID 39294443, 2024). "ZDHHC20, upregulated by KRAS, is abnormally overexpressed and associated with poor prognosis in patients with pancreatic cancer." (PMID 38821916, 2024).
pancreatic cancer (continued). "The aim of this study was to evaluate the diagnostic and prognostic value of KRAS-mutated cftDNA detection-based liquid biopsy of plasma and bile in patients with various pancreatic neoplasms." (PMID 38255325, 2024). "The KRAS gene is crucial in initiating and maintaining pancreatic tumors and is responsible for encoding a member of the Ras family of small GTPases." (PMID 38893220, 2024). "Patients at high risk of developing pancreatic cancer were administered a KRAS peptide vaccine with a poly-ICLC adjuvant on weeks 1, 3, and 5 of the initial treatment phases." (PMID 39329742, 2024). "Mutations in KRAS gene are the most abundant (more than 90%) genetic alterations in pancreatic cancer patients." (PMID 38954230, 2024). "According to the ESMO Clinical Practice Guidelines for pancreatic cancer, KRAS mutation is recognized as a genetic biomarker of disease because of its critical role in driving oncogenesis." (PMID 39767746, 2024). "The results of this retrospective cohort study showed that KRAS gene mutation, hyperlipidaemia, pancreatitis, and pancreatic cysts are significantly associated with the risk of developing pancreatic cancer." (PMID 39640479, 2024). "For example, KRAS mutations occur in over 90% of pancreatic cancer cases, however is considered to have low expression in the pancreas, compared to other organs." (PMID 39372214, 2024). "Regarding fragment size, they showed that in pancreatic cancer samples, a substantial proportion of the mutated KRAS fragments were shorter than 100 bases." (PMID 38511142, 2024). "Treatment decisions are currently based solely on cTNM staging, even though prior studies have demonstrated the prognostic relevance of KRAS mutations, which are an early and almost universal event in pancreatic cancer development." (PMID 39456638, 2024). "KC mice conditionally express endogenous mutant KRAS alleles in pancreatic cells and develop pancreatic tumors with pathological, physiological, and molecular features similar to human PDAC." (PMID 38287020, 2024). "The KRAS G12D mutation contributes to regulatory T-cell conversion through activation of the MEK/ERK pathway in pancreatic cancer." (PMID 38481800, 2024). "Using a custom panel built for 62 pancreatic cancer genes, they found cancer specific mutations in 88% of the samples, and KRAS-specific mutations in 70% of the samples, which was consistent with the tissue-based sequencing." (PMID 38511142, 2024). "Overall, our findings underscore the distinct metabolite changes induced by KRAS status, shedding light on the diverse metabolic pathways implicated in pancreatic cancer cells." (PMID 38672219, 2024). "Taken together, these findings indicate that KRAS mutations are one of major causative factors for STAT3-ZDHHC20 axis hyperactivation in pancreatic cancer." (PMID 38821916, 2024). "The pancreatic tumor was notable for dense stroma and a remarkably high mutation rate of KRAS, which was found to be as high as 90%." (PMID 38424455, 2024). "Mapping of identified metabolites to KEGG pathways identified nine significant metabolic pathways associated with KRAS status, indicating diverse metabolic alterations in pancreatic cancer cells." (PMID 38672219, 2024). "Both logistic regression and machine learning confirmed that KRAS gene mutation, hyperlipidaemia and pancreatitis are potential risk factors for pancreatic cancer." (PMID 39640479, 2024). "The most common genetic alterations in pancreatic cancer include KRAS (Kirsten rat sarcoma virus) mutations, which are present in approximately 90% of cases." (PMID 39458955, 2024). "The prevalence of KRAS mutations in pancreatic tumors is striking, with mutations of the KRAS gene being present in 90–95% of pancreatic adenocarcinomas, making it the most frequently mutated gene in this type of cancer." (PMID 38666907, 2024).